LMO2 (LIM domain only 2)
Diseases named in the same sentence as LMO2 in open-access papers (continued):
Sharing a sentence is not in itself a finding about the gene and the disease.
cancer (continued). "Single-sample gene set enrichment analysis (ssGSEA) data showed that LMO2 was positively correlated with GSC-related transcription factors in The Cancer Genome Atlas (TCGA) GBM and cancer cell line encyclopedia database." (PMID 35805116, 2022). "Signal transducer and activator of transcription 3 (STAT3) phosphorylation in the cancer cells cultured on polymer X was upregulated by the fibronectin-integrin α5-Janus kinase 2 (JAK2) axis and maintained by the cytosolic LMO2/LBD1 complex." (PMID 36359204, 2022). "Characterization by RT-PCR and in situ hybridization showed cancers express both tal1/scl and lmo2 (fish orthologues of known human T-ALL oncogenes TAL1/SCL and LMO2), emulating the most common molecular T-ALL subtype in patients." (PMID 31731471, 2019). "Of course, in the case of the human LMO2 chromosomal translocation T-ALL, cancers arise from single cells due to the rarity of the relevant translocation." (PMID 26108219, 2015). "Kit is involved in many cancers and is regulated by the SCL complex (Gata1/2, SCL, Lmo2) in haematopoietic cells." (PMID 20102610, 2010). "LMO2-driven activation of STAT3 signaling requires the LDB1 protein and leads to increased expression of an inhibitor of differentiation 1 (ID1), a master regulator of cancer stemness." (PMID 35805116, 2022). "We identified non-coding hotspots upstream of three known T-ALL oncogenes (LMO1, LMO2, and TAL1), demonstrating that hotspot detection could be useful even in small cancer cohorts." (PMID 32550006, 2020). "An intestinal immune network for IgA production might provide new markers in enteric DLBCL, such as CCR10, TNFRSF13B, AICDA, and HLA-DOB, as well as genes involved in transcriptional misregulation in cancer (NFKBIZ, FUT8, LMO2, CCND2, BCL2A1, ETV6, and CDK14)." (PMID 29992138, 2018). "Inhibition of the LMO2 protein complex in mouse models of T cell neoplasia show that LMO2 is necessary, but not sufficient, for the cancers, but that it is required at the stage of overt disease." (PMID 26108219, 2015). "In addition to the genes related to the immune system, our findings also demonstrated that treatment with Cy down-regulates the expression of several genes (e.g., Ras, LMO2, MCM4 and MCM7) that are related to cancer development and cell cycle progression." (PMID 24466173, 2014). "From limited sample material, we detected integration events in 2,749 cells and found no integration events at genomic loci associated with clonal expansion after gene therapy near LMO2, IKZF1, CCND2, HMGA2, or MECOM, and no overrepresentation near cancer-related genes." (PMID 39532107, 2025). "Additionally, Lmo2 expression in transgenic mice leads to an aggressive T-ALL, and perhaps, it is unlikely that Lmo2 expression changes a progenitor cell into a stem cell-like state for cancer." (PMID 34575830, 2021). "We detected 40 somatic mutations, including 10 mutations in genes recorded in the cancer gene list (Table EV1); primarily, we observed recurrent Notch1 (SNVs 5/10, indels 5/10) and KRas (SNVs 1/10) mutations, consistent with Rosa26‐Lmo2 + Sca1‐Cre and human LMO2+ T‐ALL pathogenesis." (PMID 29880602, 2018).
tumor (39 papers, 2008 to 2026). "Recently, 12 ETP-ALLs were analyzed by whole genome sequencing and one tumor had an interstitial deletion 5′ of LMO2 and another had a deletion of RLIM which encodes an E3 ubiquitin ligase for the LMO2/LDB1 proteins." (PMID 24465765, 2014). "Patients with presence of BCL2, CCND2, BCL6 and LMO2 mRNA in plasma showed higher expression levels for each gene in tumor tissue, although we only observed a significant association for BCL2 mRNA." (PMID 20016842, 2009). "One patient with a deletion at the LMO2 locus harbored an additional point mutation on the other allele indicating that LMO2 might be a tumor suppressor frequently targeted by 11p deletions." (PMID 24147083, 2013). "Besides, LMO2 deficiency weakened the anti-tumor effect of PARPi on NKTCL cells." (PMID 37442994, 2023). "Oncogenes show specific activity in tumor cells, with LMO2, LYN, TNFRSF17, CARD11, and BCL7A being active in Tumor B1, while BCL2 and WAS are specifically active in Tumor B2." (PMID 41238550, 2025). "In contrast, infection by pHV LV resulted in identification of 3762 (seven-fold increase) DEG of which 81 oncogenes and 82 tumour suppressor genes, that included MECOM, LMO-2 and BRAF genes previously associated with genotoxicity." (PMID 40664913, 2025). "LMO2 is a tumor suppressor which acts through the regulation of the Wnt pathway in several tumor types." (PMID 37843125, 2023). "The downregulation of LMO2 occurs due to the establishment of tumorigenesis, inhibiting apoptosis and promoting cell proliferation, migration, invasion, and tumor growth through the Wnt signaling pathway." (PMID 36661515, 2023). "Only two out of three lowly expressed TFs, namely GATA1 and LMO2, exhibited more than a two-fold change in tumor parts." (PMID 35743687, 2022). "Biochemical analyses of Lmo2 protein complexes in blood tumor cells revealed that Lmo2 organizes large transcriptional complexes with bHLH and GATA family members." (PMID 36126774, 2022). "Under these conditions, the oncogene (LMO2) is fundamental and necessary for the transformation and maintenance of the cell where the tumor originates (the committed-T cell)." (PMID 31380372, 2019). "The presence of Lmo2 is necessary for the early stages of transformation, but the final tumor phenotype is determined by the niche." (PMID 29880602, 2018). "Fluorescent activating cell sorting (FACS) analysis of leukemic cells revealed an immature CD8+CD4+/− cell surface phenotype with Lmo2 expression in the tumor T cells and clonal immature T‐cell receptor (TCR) rearrangement." (PMID 29880602, 2018). "The upregulated Rosa26‐Lmo2 + Sca1‐Cre signature shows a significant enrichment in the human T‐ALL group which is in accordance with the human T‐ALL situation wherein the expression of LMO2 is present throughout in tumor cells." (PMID 29880602, 2018). "Malignant T cells were primarily either double‐positive for CD4/CD8 or single‐positive for CD8 or single‐positive for CD4, with Lmo2 expression in the tumor T cells." (PMID 29880602, 2018). "We showed that tumour cell DNA insertions identified in this way can be further studied to establish functional significance, and confirmed that an insertion at the LMO2 locus produces enhancer function in MOLT4 T-ALL cells." (PMID 28181482, 2017). "Both ELF2A and ELF2B uniquely interact with the haemopoietic transcriptional co-regulator and proto-oncogene LMO2 whilst ELF1 specifically interacts with the tumour suppressor RB1." (PMID 28351373, 2017). "Subsequent studies on its role in tumours and in normal settings have highlighted LMO2 as an archetypical chromosomal translocation oncogene, activated by association with antigen receptor gene loci and a paradigm for translocation gene activation in T-ALL." (PMID 26108219, 2015).
tumor (continued). "It is noteworthy nevertheless that widespread transgenic expression of LMO2 from a Metallothionine promoter only resulted in T cell tumour phenotype, implying that the tumourigenic effect in mice is restricted to the T cell lineage." (PMID 26108219, 2015). "BCL2, MYC, CCND2, BCL6 and LMO2 expression was studied in tumor tissue from 12 DLBCL patients of our series using real-time PCR." (PMID 20016842, 2009). "Remarkably, this tumor has two insertions at Il2rg that occurred independently suggesting strong selection for Il2rg deregulation in Lmo2-initiated T-ALL." (PMID 19461887, 2009). "Multiple genetic drivers of T-ALL, including activating mutations in NOTCH1, deletion of the CDKN2A tumor suppressor locus, and aberrant expression of transcription factors, such as T-cell acute lymphocytic leukemia 1 (TAL1) and LIM domain only 2 (LMO2), have been identified." (PMID 37805579, 2023). "Rather than the involvement of Lmo2 in the causation of CVDs, it mostly contributes toward tumor angiogenesis resulting in the nourishment and spread of the tumor and therefore serves as an anti-angiogenic drug target." (PMID 33193725, 2020). "We propose that in human T‐ALL, genetic alterations of LMO2 may act in a hit‐and‐run fashion in early precursors, while evolved tumor cells are reliant on alternative oncogenic mechanisms." (PMID 29880602, 2018). "However, there is another possible way of interpreting the specific relationship between LMO2 and T‐ALL, and it is to consider that the LMO2 oncogene is directly capable of imposing the phenotypic characteristics of the tumor in a non‐T target cell." (PMID 29880602, 2018). "This might be the molecular basis explaining why LMO2 could function as either an oncogene or a tumor suppressor in different kinds of tumor." (PMID 27779255, 2016). "Taken together, the data in this study revealed a novel crosstalk between LMO2 and the Wnt signaling pathway during tumorigenesis and suggested that LMO2 might be a tumor suppressor in certain solid tumors, in contrast to its traditional oncogenic role in the hematopoietic system." (PMID 27779255, 2016). "Prdm16 is also insertionally mutated in two of the murine T-ALLs with Lmo2 insertions so this gene's involvement in tumor induction might not be limited to the myeloid lineage." (PMID 19461887, 2009). "Among them, GATA1, RARA and LMO2 were lowly expressed, while E2F4 and CTBP2 were highly expressed in tumor parts." (PMID 35743687, 2022). "To examine the significance of upstream genes involved in STAT3 activation regulating properties of tumor spheroids, we knocked down FN1, ITGA5, JAK1, JAK2, LDB1, and LMO2 from the cells." (PMID 36359204, 2022). "In Burkitt-like lymphoma with the 11q aberration, the expression patterns of LMO2, CD38, and c-Myc in the tumor cells were similar to those in BL tumor cells." (PMID 31484540, 2019). "Together, these data support a novel function of Lmo2 in mice, where the cell‐of‐origin differentiation state does not dictate the Lmo2 tumor cell identity." (PMID 29880602, 2018). "The identification of TAL1, LMO2 and LYL1 as new critical regulators of ANG-2 expression definitively establishes the important role of these factors in endothelial cells, and more particularly in tumor angiogenesis and development." (PMID 22792348, 2012). "Although none of them have a known causal role in tumor formation, they might influence the timing and function of the targeted genes, thus predisposing for the T-ALL29 in combination with the LMO2-activating insertion." (PMID 38688902, 2024). "Under this hypothesis, LMO2 oncogene is directly capable of priming the phenotypic characteristics of the tumor in a non-committed T cell that could be an HS/PC." (PMID 31380372, 2019). "Thus, Lmo2 has the power and capacity to switch from a B‐cell fate to a T‐cell neoplasia, although Lmo2 does not seem to contribute to the generation of normal T lymphocytes." (PMID 29880602, 2018).
tumor (continued). "Importantly, expression of the other 6 highly related zebrafish lmo family members — lmo2, lmo3, lmo4a, lmo4b, lmo5, lmo6, lmo7a, and lmo7b — was much lower than lmo1 in the GATA/GATA fish and showed no appreciable differences between the 3 tumor genotypes." (PMID 37183825, 2023).
infection (6 papers, 2009 to 2025). The state of being infected such as from the introduction of a foreign agent such as serum, vaccine, antigenic substance or organism. "To test this hypothesis, we isolated cKit+ cells from mouse fetal liver cells, cultured them for 5 days in presence of mSCF and mTpo upon infection with lentiviruses expressing control shRNA or shRNA directed against Fli-1 or Lmo2 mRNA to repress their expression." (PMID 33733070, 2021). "While these population-level effects are strong, data at the single-cell level indicate that subsets of EBV-infected cells in both early infection and LCLs retain or upregulate DZ mRNA for CXCR4, FOXO1, AICDA, IL2RB, AURKC, and LMO2." (PMID 38059622, 2024).
hematological tumors (2 papers, 2018 to 2022). "Analysis by LC-MS/MS identified more than 600 Lmo2-interacting molecules in physiological LPs, including the previously reported components of Lmo2 complexes in hematological cancer cell lines, Lyl1, Tal1, Ldb1, Tcf12, Tcf3, and Cbfa2t3 (also known as ETO2 or MTG16)." (PMID 36126774, 2022). "However, despite frequent alterations of Lmo2 in hematologic tumors, its impact on lineage organization during leukemogenesis and the importance of the cell‐of‐origin for heterogeneity and aggressiveness of Lmo2‐driven tumors have remained unclear." (PMID 29880602, 2018). "Notably, in addition to T‐ALL, LMO2 is expressed in hematologic cancer of the B‐cell lineage including DLBCL and BCP‐ALL." (PMID 29880602, 2018). "LIM domain only 2 (Lmo2) organizes large transcriptional complexes with basic helix-loop-helix (bHLH) and GATA family members and others in hematological tumors." (PMID 36126774, 2022).
cardiovascular disease (1 paper, 2022). "The data generated from both the human in silico and zebrafish in vivo assessments undertaken supports further investigation of the potential roles of API5, HSPB7, and LMO2 in human cardiovascular disease." (PMID 35548346, 2022).
LMO2 also shares sentences with these, for which no sentence is quoted: stem cell leukemia (3 papers); hepatocellular carcinoma (2); lymph node metastasis (2); lymphoid neoplasm (2); amyotrophic lateral sclerosis (1); autism (1); cervical cancer (1); chronic lymphocytic leukemia (1); dilated cardiomyopathy (1); follicular lymphoma (1); gastric cancer (1); hematological disorders (1); kidney cancer (1); lymphoblastic lymphoma (1); myeloid leukemia (1); Obesity (1); thymic lymphomas (1); thymoma (1); triple-negative breast carcinoma (1); tumors of the salivary gland (1); WAGR syndrome (1); Wiskott-Aldrich syndrome (1).